SMAD4 (SMAD family member 4)
Diseases named in the same sentence as SMAD4 in open-access papers (continued):
Sharing a sentence is not in itself a finding about the gene and the disease.
tumor (continued). "Interaction of tumor cells with stromal myeloid cells and reaction to stromal chemokine are altered with loss of Smad4." (PMID 33117687, 2020). "TGFβ-induced EMT is commonly linked with tumor progression; however, a study demonstrated that TGFβ can also induce a SMAD4-dependent lethal EMT in PDAC cells." (PMID 32429474, 2020). "And SMAD4, the protein encoded by SMAD4 gene, acts as a tumor suppressor, mainly by serving as the core mediator of transforming growth factor-beta (TGF-β) signaling pathway." (PMID 33117720, 2020). "For example, whereas subtype-1 tumours exhibit hyperactivation of mTOR-associated signalling, subtype-2 tumours display increased activation of SMAD4-associated signalling." (PMID 31988390, 2020). "DPC4 (deleted in pancreatic carcinoma locus 4), for instance, was identified as a tumor suppressor gene in carcinoma, implicated in Smad4 signaling." (PMID 32508821, 2020). "One possibility is that the loss of Smad4 signaling in tumor epithelial cells results in tumor-promoting activation of the tumor microenvironment through mechanisms of intercellular crosstalk." (PMID 33424832, 2020). "The study further showed that SMAD4 loss was associated with resistance to chemotherapy, and decreased tumor immune infiltration." (PMID 32686686, 2020). "Decrease or loss of Smad2 and Smad4 was significantly associated with advanced tumor stage (p < 0.001, p = 0.003, respectively)." (PMID 31238579, 2019). "Conversely, high Smad2 and Smad4 expression was linked to low tumor grade (p = 0,003, p = 0.048, respectively), and low tumor stage (p < 0.001, p = 0.003, respectively)." (PMID 31238579, 2019). "SMAD4-deficient CRC cells also produce C-X-C motif chemokine ligand CXCL1/8 to recruit its corresponding receptor CXCR2+ tumor-associated neutrophils (TAN)." (PMID 31756952, 2019). "SMAD4 deletion in CRC cells decreased the number of S100A8+ monocytes or CD68+ TAMs in the tumor microenvironment; this is associated with unfavorable prognoses in CRC patients." (PMID 31756952, 2019). "In particular, BAP1 mutation was detected in the primary tumour and only in one of the three liver lesions, whereas SMAD4 mutation was detected exclusively in one metastatic lesion but not in the primary tumour." (PMID 30306561, 2019). "Tumor mucin content was significantly correlated with mutations involving the MH2 domain of the SMAD4 protein (P = 0.0338)." (PMID 30730996, 2019). "In the tumor microenvironment of SMAD4-deficient CRC, TANs are recruited via the chemokine CXCL1/8-CXCR2 axis." (PMID 31756952, 2019). "Among the genes on chromosome 18q21, SMAD4 is the established tumor suppressor gene, and loss of SMAD4 disrupts canonical TGF-β signaling because it is a transcription factor for the signaling." (PMID 31756952, 2019). "SMAD4 is viewed as a tumor suppressor because it is frequently mutated or deleted in many cancer types, especially in PDAC." (PMID 31569425, 2019). "Our previous investigations concluded that SMAD4 deficiency altered the histological phenotype of KrasG12D-initiated neoplasms." (PMID 31480737, 2019). "Stable loss of SMAD4 in microglia decreased expression level of a tumor promoter, MMP9, which resulted in decreased migratory potential of microglia in a transwell migration assay." (PMID 29861845, 2018).
tumor (continued). "Again, this heterogeneity likely originates from early events in the tumour cells that impact on the stromal cells (for instance a SMAD4 mutation), but it is also possible that stochastic or epigenetic events in the stromal gene expression pattern drive this." (PMID 29382042, 2018). "Characteristically, the recurrently mutated genes in CRC, with the exception of PIK3CA and SMAD4, show a low degree of discordance between the primary tumor and the synchronous liver metastasis, confirming their biological role as driver “trunk” mutations." (PMID 30282914, 2018). "The prevalence of KRAS and SMAD4 mutations in the Control cell lines was 50% and 17%, respectively, whereas that in cancer type– and sample size–matched clinical tumor populations was 48% and 2.5%, respectively." (PMID 30220971, 2018). "Conversely, the loss of Smad4 with a resultant increase in TGF-β aids in tumor progression through the activation of Smad4-independent signaling pathways." (PMID 28067794, 2017). "Loss of SMAD4 occurs at a later stage of disease and has been associated with tumor metastases in PC." (PMID 28383487, 2017). "Further studies have shown that Smad4 loss markedly promotes tumor development initiated by Kras G12D activation and Kras G12D/Smad4−/− tumors exhibited both increased proliferation and tumor stromal formation." (PMID 28067794, 2017). "Targeted NGS analyses showed the same KRAS and SMAD4 mutations in both the tumour of the upper lobe and one of the tumours in the lower lobe." (PMID 28347348, 2017). "This seemingly contradicts our findings, where both loss of SMAD4 and overexpression of TGFβ1 in the tumor microenvironment correlated with increased myeloid cell infiltration." (PMID 27270652, 2017). "This table depicts the overall association of LOH and phenotypic expression of the protein as well as stage-specific associations after adjustment for Smad4 status, tumor stage, tumor grade, and location." (PMID 28423626, 2017). "The association between the abnormal variations in Smad4 and overall patient survival and by tumor stage was evaluated." (PMID 28423626, 2017). "We compared the demographic and clinical characteristics of our patients according to SMAD4 mutational status and found that SMAD4 mutation was associated with sex and tumor site." (PMID 28267766, 2017). "It has been suggested that loss of SMAD4 expression is an independent prognostic factor associated with tumor progression, epithelial-mesenchymal transition (EMT) and therapy failure." (PMID 28383487, 2017). "The role of TGFβ as a tumor suppressor is substantiated by previous work identifying epithelial loss of SMAD4, indicative of disrupted TGFβ signaling, in the progression of sporadic microsatellite stable advanced colorectal tumors." (PMID 27270652, 2017). "In cancer cells, allelic deletion of Smad4 is a mechanism attributed to the loss of TGF-β tumor-suppressive activities." (PMID 28423626, 2017). "In the metastatic samples, SMAD4 expression was lost in 43 cases (59.7%) whereas in the primary tumor samples SMAD4 loss was detected in slightly higher rates (49 of 71 cases, 69.0%), a difference that was not statistically significant (p = 0.162)." (PMID 28534865, 2017). "Mutations in tumor suppressors, such as SMAD4, SMAD4, and CDKN2A, are required for carcinogenesis in addition KRAS mutation." (PMID 28794854, 2017). "The phosphorylated Smads form complexes with Smad4, and these complexes accumulate in the nucleus and regulate gene transcription, including p27, which is linked to dormancy induction in many tumor cells." (PMID 27819283, 2016).
tumor (continued). "In the current study, we employed a transplanted mouse model to determine the signature of immune profiling (SIP) of tumor infiltrating lymphocytes (TILs) in the SCCs caused by KrasG12D mutation and Smad4 loss." (PMID 27835902, 2016). "PPP2R1A (E370X), SETD2 (I1608V), SMAD4 (G382T), and AR splicing site mutations were determined to be potential metastatic tumor-specific mutations." (PMID 27023146, 2016). "Here, we established a mouse model by injecting tumor cells derived from primary SCCs harboring KrasG12D mutation and Smad4 deletion into wild-type (wt) or CD8−/− recipients." (PMID 27835902, 2016). "SMAD4 deficiency has been widely associated with TGF-β resistance of tumor cells, contributing to accelerate the malignant progression." (PMID 26883911, 2016). "The findings reported here provide new insights into the mechanism by which point mutations in Smad4 cause their rapid degradation in tumor cells." (PMID 27308538, 2016). "For example, SMAD4 was mutated in 1.2% of ER+ and 1.0% ER− tumours, but had a high TSG score only in ER+ cases (ER+=35%, ER−=0%)." (PMID 27161491, 2016). "Smad4 deletion or mutation can induce precancerous diseases, promoting tumor development and affecting the biological behavior of these tumors, such as tumor invasion and metastasis." (PMID 25452807, 2015). "Loss of Smad4 expression was associated with tumor size (P = 0.033), lymph node metastasis (P = 0.014), pathological stage (P = 0.017), and tumor differentiation (P = 0.022)." (PMID 25890228, 2015). "Of note, chr18 also harbors SMAD4, which is a known tumor suppressor gene and has been shown to be associated with poor prognosis in several tumor types when lost." (PMID 26467651, 2015). "Mutation of TGFβ-R-II or copy loss of Smad4 was observed in one tumor each and implicated as a genomic driver in 2/11 MYH9 mutant tumors, a frequency similar to that for these individual genes in the overall dataset." (PMID 26369831, 2015). "Because of its mediatory role in the growth-inhibitory effects of TGF-β in normal cells and its loss in some tumors, Smad4 is considered a tumor-suppressor gene." (PMID 25890228, 2015). "The importance of SMAD4 loss-of-function in PDAC carcinogenesis is supported by the fact that SMAD4 inactivation is observed in most tumours." (PMID 24393789, 2014). "In IPMN, loss of Smad4/DPC4 has been reported to be associated with invasive tumor growth, nevertheless, it has been found to present an early change in the progression of these tumors." (PMID 25009661, 2014). "The immunohistochemical results support our in vitro data that SMAD4 is important in maintaining N-cadherin expression, and that loss or mutation of SMAD4 can change a patient's local tumor environment through altering the N-cadherin level." (PMID 25264609, 2014). "SMAD4 mutational status in case LGSC-12 was also consistent among 6 tumor samples from 4 different sites in the primary and recurrence, and despite multiple treatment cycles." (PMID 25523272, 2014). "The tumor suppressor gene SMAD4 encodes a transcription factor that is activated through signaling by members of the transforming growth factor-β (TGF-β) superfamily, including TGF-β1, Activin, and BMP." (PMID 24213498, 2012). "For the detailed investigation of Smad4's tumor suppressor functions, we stably re-expressed Smad4 via gene transfer in human Smad4-deficient SW480 tumor cells." (PMID 21492476, 2011). "Similar to spontaneous tumor formation in Smad4-deleted skin and mammary glands, Smad4 loss in head and neck tissues (HN-Smad4-/-) also developed spontaneous HNSCC." (PMID 22204491, 2011).
tumor (continued). "Further more, we found a significant association of Tumor location, Nodal status and Bleeding PR/Constipation with the mutation status of the SMAD4 gene (P =< 0.05)." (PMID 20565773, 2010). "Functional loss of the tumor suppressor Smad4 is involved in pancreatic and colorectal carcinogenesis and has been associated with the acquisition of invasiveness." (PMID 20307265, 2010). "The mutant status of KRAS and SMAD4 gene was found to be significantly associated with the higher tumor grade (C+D) (P value = 0.03)." (PMID 20565773, 2010). "For the tumor, the advantages of inactivated TGFβ signaling obviously outweigh the disadvantages, since SMAD4-deficiency is associated with a poor prognosis." (PMID 24281218, 2010). "Further more, we found a significant association of tumor location, tumor grade, node status, occupational exposure to pesticides and bleeding PR/Constipation with the mutation status of the SMAD4 gene (P =< 0.05)." (PMID 20565773, 2010). "Accordingly, as shown in our study, the majority of polyps from JPS patients carrying SMAD4 germline mutations retain SMAD4 expression both in epithelial tumor cells and in their stromal microenvironment, thus indicating haploinsufficiency." (PMID 19014666, 2008). "In these cases, as previously shown in the Smad4+/E6sad mouse model, haploinsufficiency is likely to underlie juvenile polyp onset, whereas later stages of tumor progression are accompanied by loss of the wild-type allele." (PMID 19014666, 2008). "It is plausible to think that while some SMAD4 mutations require functional inactivation of the wild-type allele to trigger tumor formation, others can result in juvenile polyp onset without this otherwise rate-limiting somatic step." (PMID 19014666, 2008). "When Smad4-deficient tumours were first identified, it was assumed that loss of TGF-β antiproliferative and proapoptotic responses underlie the tumour suppressor function of Smad4." (PMID 17997817, 2007). "At least two different Smads, Smad2 and Smad4 (DPC4), have been implicated in human cancer and appear to have tumour-suppressor functions." (PMID 9862572, 1998). "In sharp contrast, around only 0.3% of the PTEN, SMAD4 or ARID1A mutations in tumours (mean: 0.25–0.39) can be described as passengers in this way, suggesting they are true cancer driver genes positively enriched in CRC beyond their level of selection in normal tissue." (PMID 39920335, 2025). "SMAD4 mutations tend to be more common in eCCA and may be involved in tumor progression through impaired TGF-β-mediated proliferation inhibition and promotion of epithelial–mesenchymal transition." (PMID 41008893, 2025). "Physiological role: The SMAD4 gene encodes the SMAD4 protein, which has a key role as a tumor suppressor, being closely implicated in the transforming growth factor beta (TGF-β)/SMAD signaling pathway, regulating ECM production, cell growth, differentiation, and apoptosis." (PMID 41369383, 2025). "Notably, approximately 60% of PDAC cases present with an SMAD4 mutation, leading to the loss of its tumor suppressor function in canonical TGF-β signaling." (PMID 40075563, 2025). "The loss of SMAD4 expression occurs in the late stages of PDAC tumor progression." (PMID 40264765, 2025).
tumor (continued). "However, further studies to uncover additional coding/non-coding targets of METTL3, direct targets of miR-146a-5p, and upstream/downstream targets of SMAD4 responsible for its tumor-associated function in OSCC need to be probed." (PMID 40338154, 2025). "There appears to be less consistency in the observation of changes in the CDKN2A and SMAD4 tumour suppressor genes, with estimates for their functional loss ranging from 15% to 60%, perhaps contributed by different assessment technologies and differences between the analysed populations." (PMID 40723241, 2025). "Notably, combining SBRT with PARP inhibitors such as olaparib in SMAD4-deficient models significantly suppressed tumor growth, identifying a promising radiosensitization strategy." (PMID 40725389, 2025). "Interestingly, a stop-to-sense variant in the tumour suppressor gene SMAD4, leading to its rapid degradation, has been observed in multiple cancers." (PMID 39140134, 2024). "Furthermore, Smad4 deficiency in macrophages promoted MC38 tumor growth in myeloid-specific Smad4 deficient (Lyz Smad4-/-) mice, whereas blocking Fabp2 expression reversed the tumor growth." (PMID 39664586, 2024). "Subsequent studies have demonstrated that suppressing Fabp2 expression weakened macrophage M2 polarization and lipid metabolism following macrophage-specific Smad4 depletion, and effectively reversed the accelerated MC38 tumor growth caused by myeloid cell-specific Smad4 deletion." (PMID 39664586, 2024). "Moreover, loss-of-function mutations in the SMAD4 tumor-suppressing gene encoded on chromosome 18q, which is a key mediator of TGFβ signaling, are involved in the late stages of the conventional pathway." (PMID 38731846, 2024). "We also demonstrated that recruitment of CXCR2+ myeloid cells to SMAD4-deficient CRCs could promote tumor invasion and metastasis, suggesting blockade of the CXCL1/8–CXCR2 axis could be a novel therapeutic approach in CRC." (PMID 38750114, 2024). "Smad4 may play various roles in tumor development at different stages and within different mutational contexts, resulting in significant individual variations." (PMID 40458305, 2024). "Furthermore, through SMAD4, BI sup induces the loss of tumor cohesion mediated by TGF-beta, making it an attractive therapeutic target." (PMID 39113194, 2024). "Mutation of SMAD4 results in loss of the tumor suppressor function of canonical TGF-β signaling." (PMID 38500662, 2024). "In many cancers, high expression of Smad4 could suppress tumor growth and metastasis, and loss of function of Smad4 promotes tumor progression." (PMID 39253139, 2024). "However, consistent with results from the other two models, the anti-metastatic effect of BMP4 was retained in 4T1.2 tumor-bearing mice despite total loss of SMAD4." (PMID 38689334, 2024).